AHR (aryl hydrocarbon receptor)
Diseases named in the same sentence as AHR in open-access papers (continued):
Sharing a sentence is not in itself a finding about the gene and the disease.
Obesity (132 papers, 2009 to 2026). Accumulation of substantial excess body fat. "AHR signalling is markedly altered in individuals with metabolic disorders such as obesity, diabetes, and hypertension, conditions closely linked to severe COVID-19 outcomes." (PMID 40949107, 2025). "Mice deficient in AhR expression were resistant to high fat diet (HFD)-induced obesity and had increased gene expression for energy expenditure through increased brown fat UCP1-linked thermogenesis and muscle fatty acid β-oxidation." (PMID 40867852, 2025). "AhR deficiency protected against HFD-induced obesity, hepatic steatosis, insulin resistance and inflammation." (PMID 40867852, 2025). "Hepatic Trp metabolism via tryptophan 2,3-dioxygenase (TDO2) and indoleamine 2,3-dioxygenase (IDO) generates kynurenine (Kyn), which activates aryl hydrocarbon receptor (AHR) signaling to promote obesity-associated hepatic steatosis." (PMID 40556760, 2025). "Instead, the whole-body deficiency of AhR protected mice from high-fat diet-induced obesity through increased energy expenditure." (PMID 38931457, 2024). "Constitutive androstane receptor (CAR) activation and aryl hydrocarbon receptor (AHR) deficiency protected mice from HFD-induced obesity." (PMID 37069663, 2023). "Nevertheless, previous studies reported contradictory results, suggesting that AhR can be deleterious and plays a large and broad role in obesity and associated complications." (PMID 38136564, 2023). "It is also noteworthy that AhR can be activated by lipid peroxidation products which can be elevated in obesity (see ‘Genome instability and mutation’)." (PMID 36038791, 2022). "To date, epidemiological studies have suggested that persistent exposure to environmental contaminants such as dioxins, with subsequent AhR activation increases the risk of specific comorbidities such as obesity and diabetes." (PMID 36418969, 2022). "It is now well established that AhR deficiency protects mice from high-fat diet (HFD)-induced obesity." (PMID 35887027, 2022). "AhR has been implicated in the regulation of energy metabolism and is currently being investigated as a potential therapeutic target for obesity." (PMID 35202251, 2022). "In fact, TCDD-mediated activation of AhR has been linked to dioxin-driven diseases such as obesity and diabetes, atherosclerosis, diverse cancers, and kidney disease." (PMID 35448550, 2022). "For example, tissue-specific inhibition of AHR through expression of Cre from an adiponectin promoter (i.e., in mature adipocytes) caused an increase in obesity in mice on a high fat diet." (PMID 34418449, 2022). "On the other hand, pregravid obesity was associated with up-regulation of immunoregulatory molecules such as AHR (1.44-fold), CD52 (1.21-fold), and CD163 (1.8-fold)." (PMID 34195568, 2021). "In contrast, AhR deficiency in mature adipocytes through expression of adiponectin-Cre resulted in obesity, enhanced fat mass, and larger visceral adipocytes, a phenotype which was exacerbated in response to a high-fat diet." (PMID 33333918, 2020). "Other groups, using whole-body Ahr knockout, have also demonstrated a protective effect of AHR loss against HFD-induced obesity." (PMID 32730300, 2020). "Aryl hydrocarbon receptor (AHR) agonists such as dioxin have been associated with obesity and the development of diabetes." (PMID 32730300, 2020). "It has been shown, for example, that PCB77, a dioxin-like PCB that activates AHR, caused obesity in mice." (PMID 32730300, 2020). "Obesity reduces AHR signaling, causing fewer epidermal γδ T cells to round up and release cytokines upon activation, which leads to a delay in wound repair." (PMID 33291435, 2020). "More recently, the AHR was implicated in the regulation of energy metabolism and is currently being investigated as a potential therapeutic target for obesity." (PMID 33374508, 2020).
Obesity (continued). "AhR knockout mice have increased levels of energy metabolism compared with normal mice, which protects against insulin resistance, hepatic steatosis, obesity and inflammation caused by a high-fat diet (HFD)." (PMID 31638212, 2019). "Taking into account the role of inflammatory pathways in obesity and related diseases, it is important to underline that AhR activation has been shown to be enhanced by pro-inflammatory cytokines and to play a key role in inflammatory pathways." (PMID 30687113, 2018). "Activating key xenobiotic sensing transcription factors such as CAR, PXR, and AhR in mammals alters energy utilization and is associated with alterations in lipid allocation sometimes resulting in obesity." (PMID 28542405, 2017). "PXR and AhR activation is associated with obesity or fatty liver disease, while CAR activation decreases fatty liver disease in mammals." (PMID 28542405, 2017). "Several studies have indicated the protective effects of I3C on cancers and obesity; these effects are believed to be intimately associated with the AhR-mediated pathways." (PMID 27527145, 2016). "Effect of adipocyte AhR deficiency on the development of obesity, body fat distribution, and glucose homeostasis." (PMID 25734695, 2015). "Results from the present study demonstrate that, in the setting of diet-induced obesity, deficiency of adipocyte AhR results in increased adipocyte size and adiposity." (PMID 25734695, 2015). "Because obesity has been reported to increase the total body burden of lipophilic PCBs, we examined effects of adipocyte AhR deficiency on the development of HF diet–induced obesity and glucose homeostasis in mice of each genotype administered VEH or PCB-77." (PMID 25734695, 2015). "The aryl hydrocarbon receptor (AhR) is a ligand-activated factor that regulates biological effects associated with obesity." (PMID 25942489, 2015). "Due to their long half-life and lipophilicity, they accumulate in adipocytes and participate in the pathophysiology of obesity and obesity-associated chronic inflammatory diseases through activation of the aryl hydrocarbon receptor (AhR)." (PMID 24823865, 2014). "AhR antagonists should be explored as a potential therapeutic strategy in diabetes due to their ability to reduce inflammation, improve insulin sensitivity, and mitigate obesity-associated metabolic dysfunction." (PMID 41440753, 2025). "Disturbed lipid metabolism in obesity may be associated with a reduced ability of the gut microbiota to convert tryptophan into AhR agonists." (PMID 40308638, 2025). "However, an increasing number of studies indicates that AhR plays an important role in lipid metabolism, causing lipid metabolic diseases such as obesity, non-alcoholic fatty liver disease (NAFLD), and type 2 diabetes (T2D)." (PMID 39944639, 2025). "Interestingly, B[a]P-exposed mice on a HFD were protected from obesity closely resembling the phenotype observed in studies where mice are deficient in AhR activity." (PMID 39301545, 2024). "ox-LDL can activate TLR2/4 signaling cascades that ultimately provide high levels of activated IDO1, which in turn produce excess kynurenine from the available tryptophan, thereby upregulating AHR signaling in hepatocytes and leading to obesity and associated diseases." (PMID 39125436, 2024). "Both the dysregulation of AhR and obesity have independently been associated with a variety of different cancers; however, little is known about the role of adipocyte-secreted factors as systemic regulators of AhR in distal or neighboring cells." (PMID 37958428, 2023). "AhR overexpression is associated with obesity and obesity-related inflammation." (PMID 37749614, 2023). "High circulating AhR levels are also associated with obesity and glucose dysregulation." (PMID 37749614, 2023). "Moreover, AhR deficiency protected against a high-fat diet induced steatosis, obesity and inflammation." (PMID 37284280, 2023).
Obesity (continued). "A recent study in human also found an association between AHR activation and obesity." (PMID 34418449, 2022). "AhR may be linked to obesity, because the ligand-activated AhR may disrupt fat metabolism and contribute to obesity." (PMID 36499198, 2022). "In particular, ligand-activated AhR induces NF-κB-dependent transcription of inflammatory cytokines and chemokines, and may be linked with obesity and obesity-induced peripheral and central inflammation." (PMID 36499198, 2022). "Induction of the AHR has been linked to obesity and hyperglycemia in mice." (PMID 35057467, 2022). "The increased risk of severe/fatal SARS-CoV-2 infection by high risk conditions, such as elderly age, obesity, and diabetes are mediated by these conditions having expression levels of melatonin, AhR, butyrate, and LPS that are closer to those driven by SARS-CoV-2 infection." (PMID 33562472, 2021). "Chemical inhibition of AHR has also protects against obesity caused by HFD." (PMID 32730300, 2020). "In context of the emerging multidisciplinary research about AHR signaling, further understanding of the mechanisms underlying may provide a novel therapeutic target for obesity and its related metabolic disorders." (PMID 32849564, 2020). "AHR has been implicated in mice to play a significant role in obesity." (PMID 29851973, 2018). "Indeed, AhR deficiency in mice protected against diet-induced obesity and metabolic disorders by stimulating energy expenditure through increased BAT activity." (PMID 30687113, 2018). "AHR over-activation promoted while AHR deficiency protected mice from diet-induced obesity." (PMID 27738521, 2016). "Moreover, because the bioaccumulation of lipophilic PCBs is altered with obesity and upon weight loss, we examined the role of adipocyte AhR during the development of HF diet–induced obesity and during weight loss in obese mice previously exposed to PCB-77." (PMID 25734695, 2015). "It is, then, interesting to know whether an AhR antagonist would have an opposite effects in WAT or have protective roles in development of obesity-associated disorders." (PMID 25942489, 2015). "Results obtained in this study may help elucidate roles of α-NF in adipogenesis and obesity-associated angiogenesis, and possibly, the roles of the AhR antagonists in regulating WAT functions may be clarified." (PMID 25942489, 2015). "In addition to ARNT, several proteins were also reported to be associated with obesity and the AhR, such as ER and NRF-2." (PMID 25942489, 2015). "These all suggest that the AhR or the AhR-mediated pathways might suppress obesity and its associated adverse effects, and α-NF abolished the protective roles of the AhR." (PMID 25942489, 2015). "Epidemiological studies need to be carried out to determine whether diverse AHR signaling activities in the human population are associated with obesity." (PMID 22609946, 2012). "Since innate AHR is a common feature of leptin and leptin receptor deficient mice, as well as CPEfat mice and mice with diet induced obesity (i.e. mice with reduced and mice with increased leptin concentrations) it seems unlikely that the adipokine can act as an intermediary in the causal pathway." (PMID 21040518, 2010). "Increased fat intake is associated with obesity and may make obese individuals uniquely susceptible to the effects of lipophilic aryl hydrocarbon receptor (AHR) ligands." (PMID 19750107, 2009). "Furthermore, dietary potassium may relate to Aryl hydrocarbon receptor polymorphisms which are reported to induce weight gain, glucose intolerance, and the development of obesity." (PMID 37139459, 2023). "In conclusion, these data suggested that the repression of classical AhR signaling, a phenotype driven by exposure to BMAs, is predictive of worse clinical outcomes in MM patients, supporting the evidence that MM patients with obesity have increased risk for disease progression." (PMID 37958428, 2023).
Obesity (continued). "This suggests a role for AhR in mediating interactions between metabolism and inflammatory status in obesity and T2DM." (PMID 41440753, 2025). "Our results revealed that quercetin supplementation significantly mitigated obesity and chronic inflammation, and improved the disrupted gut barrier function through the actvation of AhR/interleukin 22 (IL-22) pathway." (PMID 40308638, 2025). "AhR deficiency protects AhR−/− and AhR+/− mice from high-fat diet (HFD)-induced obesity, hepatic steatosis, insulin resistance, and inflammation, while preserving insulin signaling in major metabolic tissues." (PMID 41440753, 2025). "In individuals with comorbidities such as obesity and diabetes, AHR overactivation further exacerbates metabolic dysfunction, endothelial injury, and thrombotic risk." (PMID 40949107, 2025). "IPA supplementation alleviated obesity and chronic inflammation, and enhanced intestinal barrier function through AhR activation." (PMID 40308638, 2025). "AhR plausibly contributes to the interaction between metabolism and the proinflammatory state during the onset of obesity and in T2D patients." (PMID 41273480, 2025). "The available evidence thus appears to point to prevention or inhibition of obesity and the metabolic syndrome with impaired AHR function and, conversely, their aggravation with induced AHR activity." (PMID 40687891, 2025). "Overall, these findings extend the understanding of environmental pollutant-induced metabolic disorders and identify the hepatic AhR–PAI-1 axis as a potential therapeutic target for obesity and related metabolic diseases." (PMID 40943373, 2025). "In obesity, dietary and microbial metabolites can hyperactivate AHR, leading to insulin resistance and chronic low-grade inflammation." (PMID 40949107, 2025). "AhR activation contributes to adipogenesis, obesity, insulin resistance, and depletion of glucose stores." (PMID 41440753, 2025). "A high complexity has emerged regarding AhR functions in different diseases with clear discrepancies in tumorigenesis and other metabolic syndrome such as obesity, diabetes, and aging." (PMID 40197001, 2025). "Regarding energy balance, studies in the obesity-prone C57BL/6J mice have indicated that for feeding on a Western diet or a high-fat diet (HFD) to result in obesity, the participation of AHR is required." (PMID 40687891, 2025). "Obesity induced by environmental toxins, insulin resistance, and diabetes development are known to be mediated by the ligand-activated transcription factor aryl hydrocarbon receptor (AhR), which functions as a xenobiotic sensor." (PMID 41440753, 2025). "Recent researches in metabolic diseases showed that enhancing AhR expression promoted obesity and insulin resistance." (PMID 39979552, 2025). "Obesity induced by environmental toxins, insulin resistance, and diabetes development are mediated by the ligand-activated transcription factor (AhR), which functions as a xenobiotic sensor." (PMID 41440753, 2025). "Reduced intestinal AhR activity has been observed in a variety of chronic diseases, including obesity, MS, hypertension, and atherosclerosis." (PMID 39679283, 2024). "In mice, adipocyte-derived KYN promotes obesity and insulin resistance by activating the arylhydrocarbon receptor (AhR)/STAT3/IL-6 signaling pathway." (PMID 39125332, 2024). "It has been found that during obesity, intestinal inflammation increased, indole decreased in feces, and AhR activity decreased." (PMID 39200098, 2024). "There is substantial evidence indicating that AHR plays a role in regulating adaptive immune responses, which are relevant to the development of obesity." (PMID 39195175, 2024). "The activation of AHR promotes obesity and IR, whereas impaired AHR leads to dietary- and genetic-mediated metabolic impairments, notably glucose dysmetabolism and liver steatosis." (PMID 39426289, 2024).
Obesity (continued). "Reduced production of aryl hydrocarbon receptor (AHR) ligands by gut microflora is a crucial factor in the pathogenesis of metabolic syndromes such as obesity and diabetes." (PMID 39162538, 2024). "2H-indol-2-one-1,3-dihydro has been described to activate the aryl hydrocarbon receptor, whose activation prevents cytokine induction and defends gut barrier integrity against damage in obesity." (PMID 38904913, 2024). "Previous studies from our lab indicate that the global depletion of AhR (AhRKO) protects male mice from HFD-induced obesity and metabolic dysfunction." (PMID 37443781, 2023). "Mice with a global depletion of (AhRKO), heterozygous AhR+/− or a congenic low affinity AhR (B6.D2) are protected from HFD-induced obesity and metabolic dysfunction." (PMID 37443781, 2023). "Circulating AhR concentrations are higher in subjects with overweight or obesity than in those with normal weight." (PMID 37749614, 2023). "The tryptophan (Trp) metabolite, kynurenine (Kyn), is a fat derivative that activates AhR to promote obesity." (PMID 37443781, 2023). "On the other hand, similar to effects on weight and glucose sensitivity, preadipocyte-specific AhR depletion showed exacerbated HFD-induced obesity with larger adipocytes in males." (PMID 37443781, 2023). "The participants with obesity had a higher plasma AhR level than the controls (81.0 ± 24.5 vs. 65.1 ± 16.4 pg/mL, P = 0.010)." (PMID 37749614, 2023). "In males, adipose-specific AhR depletion delays the development of obesity and insulin resistance through the maintenance of healthy crosstalk between adipocytes and immune cells." (PMID 37443781, 2023). "The AhR plays a role in the control of body energetic metabolism, and the use of AhR antagonists has been reported to reduce obesity, adiposity or liver steatosis in mice fed with Western diet." (PMID 36077780, 2022). "This section highlights key discoveries related to AhR influences on the neuroendocrine system to control energy homeostasis and provides rationale for exploiting AhR as a therapeutic target in obesity for both the sexes." (PMID 35887027, 2022). "Specifically, Kyn stimulates AhR expression to activate the AhR/Stat3/IL-6 signaling in adipocytes, by which it mediates a systemic effect on the development of obesity and insulin resistance." (PMID 35715443, 2022). "The role of this class of chemicals in obesity remains to be further elucidated, especially when considering the hydrocarbon receptor (AhR) as the main mediator of dioxins’ toxicity." (PMID 35202251, 2022). "The role of IDO1 and AHR in developing obesity was further indicated by the facts that IDO1 and AHR knockout mice showed a significant decrease in body weight compared to WT control mice." (PMID 35154484, 2022). "The individual pathophysiological role c-Myc, cGAS/STING, IDO1, and AHR plays in inflammatory responses has been demonstrated in obesity and type 2 diabetes 69-71." (PMID 35154484, 2022). "AhR is activated by endogenous ligands such as kynurenine, whose levels rise in human obesity and which is itself metabolised into a number of products, particularly 3-HAA, which suppresses the pro-inflammatory mouse Th1 and Th17 cells." (PMID 36038791, 2022). "Protection of mice bearing a constitutively active form of AhR from diet-induced obesity and diabetes is abolished upon FGF21 knockdown." (PMID 35887027, 2022). "Some of the first evidence of AHR involvement in lipid metabolism came from a rodent ARH knock-down model which appeared to be protected against diet-induced obesity and diet-related metabolic complications such as liver steatosis." (PMID 34418449, 2022). "This is the first study to show that the novel AhR antagonist HBU651 exhibited anti-obesity and anti-inflammatory activities in BV2 microglial cells and HFD-induced obese mice." (PMID 36499198, 2022).